CHROMR (cholesterol induced regulator of metabolism RNA)
Synonyms: CHROME; PRKRA-AS1
Gene: Long non-coding RNA gene on chromosome 2 (178,413,476 to 178,442,854, forward strand). Ensembl gene ENSG00000223960.
Diseases named in the same sentence as CHROMR in open-access papers:
CHROMR is named in the same sentence as 23 diseases in open-access papers, as found by Europe PMC text mining. Sharing a sentence is not in itself a finding about the gene and the disease. The quoted sentences say what the papers report.
atherosclerosis (5 papers, 2019 to 2024). A disease characterized by the build-up of fatty material and calcium deposition in the arterial wall resulting in partial or complete occlusion of the arterial lumen. "Expression of CHROMR in both the plasma and neointima was increased in patients with atherosclerosis, with the latter being localized to the infiltrating inflammatory cells." (PMID 39049097, 2024). "Among these CHROMR-associated miRNAs, circulating miR-27b was found to be downregulated in smokers predisposed to PAD, while circulating miR-33a was found to be elevated in T2D patient serum, and inhibition of miR-33a/b reduced atherosclerosis." (PMID 39049097, 2024).
coronary artery disease (5 papers, 2019 to 2025). "Circulating CHROMR levels are elevated in individuals with coronary artery disease compared to healthy controls and are also increased in atherosclerotic plaques relative to normal arterial samples." (PMID 40559622, 2025). "In this review, we have highlighted CHROMR, a primate-specific long noncoding RNA that is upregulated in patients with coronary artery disease and plays a key regulatory role in cholesterol homeostasis." (PMID 40559622, 2025). "Furthermore, CHROMR’s genomic location is near a locus associated with plasma high-density lipoprotein-associated cholesterol (HDL-C) variation in women and linked to premature coronary artery disease, suggesting a potential regulatory role in CVD." (PMID 40559622, 2025).
viral infection (4 papers, 2023 to 2025). "Still, the impact of various environmental stimuli (i.e., viral infection versus cholesterol overload) on the subcellular distribution of CHROMR—and thus its function—remains largely uninvestigated." (PMID 40559622, 2025). "A primate-specific lncRNA CHROMR can restrict viral infection of macrophages by sequestering the IFN regulatory factor (IRF)-2-dependent transcriptional corepressor IRF2BP2, thereby promoting the transcription of the ISG network." (PMID 37108410, 2023). "Expression of CHROMR is crucial for restricting viral infections in macrophages, and CHROMR can license IRF-dependent signaling and transcription of the ISGs network by sequestering the interferon regulatory factor (IRF)-2-dependent transcriptional corepressor IRF2BP2." (PMID 40285022, 2025). "One of these (CHROMR) is induced by SARS-CoV-2 infection, coordinates expression of interferon-stimulated genes (ISGs) and restricts viral infection of macrophages." (PMID 37998395, 2023). "An interesting recent study found a primate-specific lncRNA (CHROMR) to be induced by SARS-CoV-2 infection coordinated expression of interferon-stimulated genes (ISGs), and restricted viral infection of macrophages." (PMID 37998395, 2023).
asthma (2 papers, 2022 to 2025). "Individual roles of IRF2BP2, as well as its interaction with IRF2 in the IRF2/IRF2BP2 repression complex, have been described in autoimmune diseases, including asthma, multiple sclerosis, atopic dermatitis, and psoriasis, where CHROMR has been implicated." (PMID 40559622, 2025). "Further validation of these SNPs, SNVs, and CNVs will be necessary to determine CHROMR’s potential involvement in atopic dermatitis, psoriasis, and/or asthma." (PMID 40559622, 2025). "The final two asthma-associated CNVs are partial gene duplications on chromosome 2 (affecting exons 4–8 of the PRKRA gene and the 3’ end of the CHROMR long non-coding RNA gene) and chromosome 12 (affecting exon 2 of the FBRSL1 gene)." (PMID 35597955, 2022).
autoimmune disease (2 papers, 2023 to 2025). A disorder resulting from loss of function or tissue destruction of an organ or multiple organs, arising from humoral or cellular immune responses of the individual to their own tissue constituents. "In addition, recent data, has linked CHROMR with several types of cancer, antiviral response and autoimmune disease." (PMID 36950523, 2023). "CHROMR has also been implicated in elevated risk for stomach adenocarcinoma, lung adenocarcinoma, increased resistance to chemotherapy in Lymphoma, but also in antiviral response to Influenza and COVID-19 infections and autoimmune disease, such as multiple sclerosis." (PMID 36950523, 2023).
diffuse large B-cell lymphoma (2 papers, 2024 to 2025). "Notably, CHROMR is highly expressed in diffuse large B-cell lymphoma (DLBCL) cells resistant to the anticancer drug rituximab, and its overexpression promotes cancer cell proliferation." (PMID 40559622, 2025).
glioma (2 papers, 2023 to 2025). A benign or malignant brain and spinal cord tumor that arises from glial cells (astrocytes, oligodendrocytes, ependymal cells). "CHROMR expression is also elevated in glioma, prompting investigation into its association with patient survival." (PMID 40559622, 2025). "For example, miR-27b, which CHROMR seems to be able to sponge has both been linked with glioma progression and glioma repression." (PMID 36950523, 2023). "We found that highly upregulated CHROMR in gliomas is associated with poor patient survival in TCGA samples." (PMID 36950523, 2023). "Here we report a link between glioma patient survival and the lncRNA CHROMR gene, which could be linked with the overlapped PRKRA gene in glioblastomas." (PMID 36950523, 2023). "Perhaps there is aberrant PRKRA protein function in glioma cells, resulting in a reduced ability to respond to pro-apoptotic signals, that could be caused by the observed high CHROMR expression in gliomas." (PMID 36950523, 2023). "In order to evaluate the effect of the mRNA PRKRA/lncRNA CHROMR on glioma patient outcome, we performed survival analysis." (PMID 36950523, 2023). "Survival analysis showed lower survival rates in patients with low mRNA PRKRA/lncRNA CHROMR gene expression ratio compared to high ratio showing a link between lncRNA CHROMR and glioma patient survival prognosis." (PMID 36950523, 2023). "Here we focus on the interesting role of natural antisense lncRNA CHROMR in glioma." (PMID 36950523, 2023). "It is also known that CHROMR can act as a sponge for various miRNAs, but it would be difficult to attribute miRNA sponging to observed effects on glioma." (PMID 36950523, 2023). "Since PRKRA is known to play a role in antiviral response, perhaps our observations of high levels of CHROMR in glioma could play a role in inhibiting PRKRA related antiviral (which is related to anti-tumor) response." (PMID 36950523, 2023). "In this study, we investigated the expression profiling of the most poorly understood ncRNAs species—non-coding natural antisense transcripts (ncNATs) and identified significantly upregulated expression of antisense lncRNA CHROMR in glioma as compared to normal brain tissue using RNA-seq." (PMID 36950523, 2023). "However, further experiments will have to be performed in order to elucidate the mechanism of action and other players involved in the CHROMR-Glioma link." (PMID 36950523, 2023). "Next, we checked CHROMR effect on the survival of glioma patients." (PMID 36950523, 2023). "We extracted lncRNA CHROMR and mRNA PRKRA gene expression data from our in-house glioma patient RNA-seq dataset." (PMID 36950523, 2023). "We therefore investigated gene expression levels of natural antisense lncRNA CHROMR (Cholesterol Induced Regulator of Metabolism RNA) and its sense protein coding gene PRKRA (Protein Activator of Interferon Induced Protein Kinase EIF2AK2) in gliomas." (PMID 36950523, 2023). "The fact that PRKRA/CHROMR ratio, but not the genes separately, had an effect on survival of glioblastoma patients, suggests that CHROMR may indeed have some NAT-associated interaction with the overlapped PRKRA gene in glioblastoma, but not low-grade glioma." (PMID 36950523, 2023). "Here we found that LGG and GBM samples had more than 3.0 log2-fold (3.35 and 3.04, respectively) significantly higher expression of lncRNA CHROMR than healthy brain, while expression of protein coding PRKRA mRNA did not seem to differ between healthy brain and glioma samples." (PMID 36950523, 2023).
lung adenocarcinoma (2 papers, 2023 to 2025). A carcinoma that arises from the lung and is characterized by the presence of malignant glandular epithelial cells. "Elevated levels of CHROMR were also found in lung adenocarcinoma cells and tissues." (PMID 40559622, 2025). "This study further indicated a role for CHROMR in the metastasis of lung adenocarcinoma." (PMID 40559622, 2025).
multiple sclerosis (2 papers, 2023 to 2025). A progressive autoimmune disorder affecting the central nervous system resulting in demyelination. "CHROMR was found to be associated with an SNP (rs9283487) with genetic risk for multiple sclerosis and Sjögren’s syndrome." (PMID 40559622, 2025). "Subsequently, expression levels of CHROMR in peripheral blood mononuclear cells of multiple sclerosis patients (n = 38) were tested by quantitative PCR and revealed a significant downregulation of CHROMR compared to a control group of healthy volunteers (n = 17)." (PMID 40559622, 2025).
acute monocytic leukemia (1 paper, 2022). Acute monoblastic leukemia (AML-M5), is one of the most common subtypes of acute myeloid leukemia (AML) that is either comprised of more than 80% of monoblasts (AML-M5a) or 30-80% monoblasts with (pro)monocytic differentiation (AML-M5b). "Finally, we verified the expression levels of CRNDE, CHROMR and NARF-IT1 in ML cell lines K562, MOLM13 and acute monocytic leukemia cell line THP-1, which were significant." (PMID 34996458, 2022).
atopic dermatitis (1 paper, 2025). "This SNV, located in an intronic region of CHROMR and the sixth exon of PRKRA, is associated with a lower estimated odds ratio of 0.55 (0.46–0.66) for atopic dermatitis and a higher odds ratio of 1.20 (1.15–1.27) for psoriasis." (PMID 40559622, 2025).
brain glioma (1 paper, 2023). A malignant glioma that involves the brain. "Our results suggest that increased CHROMR expression could be linked to development of malignancy and poorer prognosis for brain glioma patients." (PMID 36950523, 2023). "This confirms that a lower mRNA PRKRA/lncRNA CHROMR ratio (and thus a high expression of lncRNA CHROMR) is a feature of brain glioma." (PMID 36950523, 2023). "This reduced the mRNA PRKRA/lncRNA CHROMR ratio in LGG and GBM samples by a log2-fold change of 2.81 and 2.57, respectively as compared to normal brain tissue, which suggests a high expression of lncRNA CHROMR is characteristic of brain gliomas." (PMID 36950523, 2023).
lymphoma (1 paper, 2023). A malignant (clonal) proliferation of B- lymphocytes or T- lymphocytes which involves the lymph nodes, bone marrow and/or extranodal sites. "CHROMR expression is different when comparing lymphoid cancer (high) with myeloid cancer (low) cell lines." (PMID 36950523, 2023).
tumor (4 papers, 2023 to 2025). "PRKRA mRNA/CHROMR gene expression ratio was significantly lower in tumorous tissues than in normal brain samples and was associated with shorter patient survival." (PMID 36950523, 2023). "Here, CHROMR expression was directly correlated with tumor growth as well as metastasis and poor patient prognosis." (PMID 40559622, 2025). "Emerging evidence also implicates CHROMR in cancer biology, including its potential involvement in cell viability and gene regulation in various tumor contexts." (PMID 40559622, 2025). "LncRNA CHROMR was highly expressed in 47 DLBCL tissues compared to 337 corresponding para-tumor specimens by analysis of the TCGA data." (PMID 38367665, 2024). "Deeper insight into how CHROMR contributes to tumor progression, metastasis, and resistance to therapy may pave the way for novel treatment strategies." (PMID 40559622, 2025). "We also examined whether lncRNA CHROMR suppression limits DLBCL tumor growth in vivo." (PMID 38367665, 2024). "Among them, CHROMR, LNC01094, AC245041.1, and AL355574.1 had significantly higher expression levels in tumor cell lines, whereas AC005586.1, AL16178.5, and AP001528.1 had the opposite, which is consistent with the results of our analysis." (PMID 36935487, 2023). "In cancer, CHROMR binds additional miRNAs (e.g., miR-27b-3p, miR-186-5p, miR-1299) that repress cell cycle regulators such as CNNM1, MET, and NCAPG2, thereby promoting tumor proliferation and metastasis." (PMID 40559622, 2025). "In the cytoplasm, CHROMR competitively inhibits microRNAs involved in cholesterol efflux and cell cycle regulation, thereby impacting gene pathways involved in reverse cholesterol transport, HDL biogenesis, and tumor growth." (PMID 40559622, 2025). "miR-27b-3p, a tumor suppressor in DLBCL, was predicted here as a candidate target of lncRNA CHROMR." (PMID 38367665, 2024).
cancer (1 paper, 2025). A tumor composed of atypical neoplastic, often pleomorphic cells that invade other tissues. "Elevated levels of CHROMR have been reported in a variety of cancers and are directly correlated with adverse patient outcomes." (PMID 40559622, 2025). "Elevated blood levels of CHROMR have been observed in patients with cardiovascular disease and several cancers, where it is correlated with poor clinical outcomes." (PMID 40559622, 2025). "In a subsequent study of DLBCL, CHROMR was further shown to accelerate cancer progression and promote chemoresistance." (PMID 40559622, 2025). "CHROMR has also emerged as a candidate biomarker in cancer diagnostics, with correlation studies linking its expression to poor patient outcomes." (PMID 40559622, 2025). "In this review, we detail the multifaceted functions of CHROMR in cholesterol metabolism, innate immunity, and cancer progression." (PMID 40559622, 2025). "Mechanistic studies suggest that CHROMR’s impact on cancer prognosis is primarily mediated through its function as a ceRNA, mirroring its role in modulating cholesterol homeostasis in macrophages and hepatocytes." (PMID 40559622, 2025). "Collectively, these findings highlight CHROMR’s emerging role in cancer biology." (PMID 40559622, 2025). "Similar cytoplasmic functions were found for CHROMR in certain cancers where it targets miR-27b-3p, miR-186-5p, and miR-1299, repressing cell cycle-regulator genes CNNM1, MET, and NCAPG2, leading to accelerated cancer growth and progression." (PMID 40559622, 2025).
cardiovascular disease (1 paper, 2025). "By modulating cholesterol metabolism at the post-transcriptional level, CHROMR has emerged as a central player in a ncRNA network with promising therapeutic potential for cardiovascular disease." (PMID 40559622, 2025).
infection (1 paper, 2025). The state of being infected such as from the introduction of a foreign agent such as serum, vaccine, antigenic substance or organism. "CHROMR expression was similarly upregulated by IAV and SARS-CoV-2, infection, while other lncRNAs that were tested were preferably enhanced by either IAV (BISPR, NRIR, CCR5AS) or SARS-CoV-2 (LUCAT1) infection." (PMID 40559622, 2025).
CHROMR also shares sentences with these, for which no sentence is quoted: glioblastoma (1 paper); influenza (1); psoriasis (1); renal cell carcinoma (1); sarcoidosis (1); stomach adenocarcinoma (1).